CRP (C-reactive protein)
Diseases named in the same sentence as CRP in open-access papers (continued):
Sharing a sentence is not in itself a finding about the gene and the disease.
tumor (continued). "Moreover, it was indicated that some of the tumor patients (26%) who were negative for CRP presented positive concentrations of ADAM15." (PMID 40725774, 2025). "However, we reported that some of the tumor patients (26%) who were negative for CRP presented positive concentrations of ADAM15." (PMID 40725774, 2025). "However, the low levels of inflammatory markers like CRP, along with the lack of significant increase in tumor incidence in the exercised group, suggest that there was no inflammatory response, and exercise did not have unintended effects on tumor biology." (PMID 40284805, 2025). "However, it is currently unclear what direct effect CRP (of binding to B4GALT7, CHST3, etc.)may have on CS synthesis, how this alters CSPG activity, and thus whether this directly modifies tumor cell behavior." (PMID 41614767, 2025). "Pre-transplant higher serum levels of CRP and IL-6 observed in our CEPH group seem to support this hypothesis, as they may not only reflect systemic inflammation but were also shown to correlate with immune status at the tumor site." (PMID 40142840, 2025). "In addition, RAR was strongly correlated with inflammatory biomarkers, such as CRP and LYM, and positively correlated with TBIL, Child-Pugh scores, and maximum tumour diameter, suggesting that RAR has the potential to reflect inflammatory status, liver function, and tumour burden." (PMID 39781529, 2025). "As CRP reflects systemic inflammation and LDH reflects tumor burden and metabolic activity, lower values of these markers suggest that patients in the High-Alb group may have relatively attenuated inflammation and tumor progression." (PMID 41340164, 2025). "These factors included elevated levels of body mass index, PD-L1 tumor proportion score (TPS), and albumin, as well as decreased levels of serum cytokeratin 19 fragment antigen 211, neuron-specific enolase, squamous cell carcinoma antigen, platelets, and C-reactive protein (all p < 0.05)." (PMID 39930148, 2025). "Interestingly, serum albumin, CRP, preoperative tumor markers (CEA and CA19-9), PNI, and mGPS were not significantly different between the SO and non-SO groups." (PMID 39410049, 2024). "CRP had no direct effect on tumor proliferation in either cell line." (PMID 39564003, 2024). "Other stratification factors were used in literature: performance status, primary tumor localization (head vs body or tail), albumin, time since receiving most recent anticancer therapy, tumor stage at diagnosis, baseline CA19-9 number of metastatic sites, peritoneal carcinomatosis, CRP>5mg/dL." (PMID 38408958, 2024). "Furthermore, the results indicated that high CRP levels were significantly correlated with International Federation of Gynecology and Obstetrics (FIGO) stages III–IV (p < 0.001), residual tumor size ≥ 1 cm (p < 0.001), histological grade 3 (p = 0.040), and ascites volume ≥ 500 mL (p < 0.001)." (PMID 38172843, 2024). "Therefore, CRP may also contribute to tumor progression by inducing the production of IL‐6 by macrophages, followed by STAT3 activation in tumor tissues." (PMID 39564003, 2024). "Tumor markers including alpha-fetoprotein (AFP), human chorionic gonadotropin (hCG), and carcinoembryonic antigen (CEA), as well as inflammatory markers such as C-reactive protein (CRP), procalcitonin (PCT), and interleukin-6 (IL-6), were all within normal ranges." (PMID 38600577, 2024). "Moreover, CRP showed prognostic value for survival irrespective of tumour location and BRAF/KRAS status." (PMID 38613909, 2024). "Furthermore, this result persisted in a multivariate analysis (low versus high Ang-2 expression; HR = 0.49; 95% confidence interval [CI] 0.31–0.78; p = 0.003) adjusted for age, sex, stage, adjuvant therapy, radical (R0) surgery, and tumor markers CA19-9, CRP, and CEA." (PMID 37907568, 2023). "Furthermore, the WBC count and CRP level did not elevate, and the tumor disappeared; thus, the drain tube was removed at 7 days after insertion." (PMID 39516894, 2023).
tumor (continued). "As CRP production is stimulated by IL-6, an increase in CRP levels early after ICI administration may reflect the activation of immune cells, which can enhance anti-tumour immunity." (PMID 39516365, 2023). "The risk factors that increased the risk for conversion to appendectomy and/or recurrence were the presence of an appendicolith with or without calcifications, neoplasm, appendiceal dilatation, peri appendiceal fluid collection, higher mean temperature, and high CRP." (PMID 37790034, 2023). "Interestingly, ferritin, but not CRP and IL-6, was significantly (P <.05) but modestly (Spearman r < -0.3) associated with lower CAR T-cell expansion normalized to baseline tumor burden at days 7, 14, and 21 post infusion." (PMID 37153543, 2023). "On the other hand, patients characterised as CRP-increase had late CRP elevation, which may represent a tumour-derived exacerbation of inflammation rather than activation of anti-tumour immunity." (PMID 39516365, 2023). "In addition, acute phase proteins (ORM1, CRP, SAA1) and complement cascade components (SERPINA1, C5, FGA) showed an obviously significant correlation with tumor size, reflecting a positive connection between inflammatory response and tumor size." (PMID 37460463, 2023). "Although the total staging system for HCC, such as the CLIP score and C-reactive protein and AFP in immunotherapy (CRAFITY) score, includes AFP, other scoring systems, such as BCLC staging, JIS, and the ALBI-T score, basically consist of the tumor burden and hepatic reserve function." (PMID 37686624, 2023). "This hypothesis is supported by our findings on tumor size and the level of CRP at baseline, which were significantly negative correlated with the change in energy expenditure, with CRP as sole significant predictor." (PMID 37946297, 2023). "Hence, post-treatment TS and CRP concentrations were estimated for all patients and allowed for a rich assessment of non-baseline CRP concentrations and tumor shrinkage at later time points." (PMID 38001689, 2023). "We also did not have CRP levels in cohort 2 to correlate these with IL-6 expression on the tumor." (PMID 37852738, 2023). "Moreover, in applying this method, an ultrasensitive nanoplasmonic immunoturbidimetry assay (NanoPITA) was carried out for the high-throughput quantification of hypersensitive C-reactive protein (CRP), a well-known biomarker of cardiovascular, inflammatory, and tumor diseases." (PMID 36354468, 2022). "An elevated CRP level may reflect a non-specific inflammatory response to tumor necrosis, which in turn indicates the levels of inflammatory cytokines such as IL-6." (PMID 35965580, 2022). "In addition, we identified several clinical parameters (age, ECOG PS, BMI, tumor stage) as well as different laboratory parameters (CEA, CRP, and creatinine levels) as prognostic as potentially prognostic factors (p < 0.150) in univariate Cox-regression analyses." (PMID 36139589, 2022). "In fact, CRP levels prove to be modest, so neither is the result of infections or tissue lesions, nor the fundamentals of inflammation defined by Celso, such as heat (calor), pain (dolor), redness (rubor), and swelling (tumor), are present." (PMID 35742064, 2022). "The CRP value was correlated with prognosis in neither the uni-nor the multivariate analysis; this may be due to the non-specificity of this marker to tumor growth." (PMID 35804835, 2022). "Within the tumor CRP levels remained constant regardless of treatment." (PMID 36505796, 2022). "CRP showed good survival predictive value in surgical and non-surgical subgroups, radiotherapy and non-radiotherapy subgroups, chemotherapy and non-chemotherapy subgroups, different BMI subgroups, and different tumor stage subgroups." (PMID 35752767, 2022).
tumor (continued). "Pretreatment blood examinations for C-reactive protein (CRP) and albumin levels; neutrophil, lymphocyte, and white blood cell (WBC) counts; and neutrophil/lymphocyte (N/L) ratio were investigated and correlated with tumor size, tissue grade, and maximum standardized uptake value (SUVmax)." (PMID 36181081, 2022). "We found that CRP concentration evaluation in routine clinical practice may have an advantage as a prognostic biomarker in CRC patients, as this protein the most comprehensively reflects clinicopathological features of the tumor." (PMID 34441316, 2021). "We analyzed a variety of clinical factors that may be associated with CRS (gender, age, transplantation, CAR-T cell dose, bone marrow tumor burden, species of CAR, costimulatory molecules, serum maximum values of IL-6 and CRP, and minimum level of CD4/CD8) separately." (PMID 33708205, 2021). "Another recent study evaluated a preoperative scoring system based on sex, peritumoral edema, preoperative CRP value, and plasma fibrinogen level and found a Ki67 cutoff of > 6% prognostic to predict tumor recurrence but the cohort was not stratified for brain infiltration." (PMID 34800210, 2021). "Oral health or tumour-related variables did not independently affect the CRP/alb ratio." (PMID 33740951, 2021). "The cellular derived measurement did not substantially correlate to tumor diameter or CRP levels." (PMID 32621022, 2021). "Blood analysis and urinalysis, assessment of the tumor markers CEA and alpha-fetoprotein, autoimmunity tests and infective screening were performed, all within the normal range, except for an elevated C-reactive protein (CRP) value of 52.76 mg/L (normal range 0–5 mg/L)." (PMID 34440363, 2021). "Gender, age, BMI, tumor diameter, stage, differentiation, surgical methods, chemotherapy, lymphocyte count, albumin, CA19-9, hemoglobin, platelet, aspartate transaminase, alanine transaminase, pre-albumin, and CRP in the training group were included in LASSO regression." (PMID 34136406, 2021). "In this cohort, patients with neoplasms did not display CRP levels above 5 mg/L." (PMID 34830693, 2021). "Multivariate analyses revealed that high CRP was a significant negative factor for OS (HR: 7.69, 95% confidence interval: 2.43–24.3, p < 0.001), and this result was independent of Child-Pugh score and existing tumor factors." (PMID 33351844, 2020). "However, it is known that CRP is not a specific tumor marker for EC, therefore exclusion of other reasons for increased serum CRP before suspecting EC is crucial." (PMID 32977765, 2020). "Clinical outcome prediction in never-smoker LC patients may be improved by both CRP and tumor immune contexture evaluation." (PMID 32646072, 2020). "However, based on our previous observations that the CRP ASO decreased MDSC infiltration into I/R injured kidneys and that tumor challenged CRP−/− mice had decreased intra-tumor MDSCs, we predict that a CRP-specific ASO should decrease CRP-driven MDSC infiltration into tumors." (PMID 33633738, 2020). "On the other hand, IL‐6 secreted by GBM acts on hepatocytes and may secrete high levels of CRP through the janus kinase‐signal transducer and activator of transcription (JAK‐STAT) pathway, which reaches the tumor site through blood circulation and then accumulates in tumor tissue." (PMID 31599129, 2019). "Good efficacy of anti-PD-1 antibodies was observed in combination with other therapeutic modalities (such as antiangiogenesis, intratumoral interferon injection, and tumor-infiltrating lymphocytes) and in the presence of elevated serum CRP levels without liver metastasis." (PMID 31662753, 2019). "However, at present one cannot rule out that CRP has no direct effect on tumors but rather displays a down-stream effect of IL-6 mediated tumor progression." (PMID 31788452, 2019).
tumor (continued). "These analyses suggest that the prognostic usefulness of the inflammatory markers PLR and CRP (but not NLR) may be due to their reflection of parameter values for tumour growth and invasiveness." (PMID 30662766, 2019). "Similarly, this effect of platelets on KLF6 expression was independent of direct contact between platelets and tumor cells because pellets of CRP-activated platelets did not affect the expression of KLF6 in HCC cells." (PMID 28638139, 2017). "Elevated CRP serum concentrations in the absence of other reasons for increased inflammatory parameters may indicate tumor recurrence." (PMID 28514756, 2017). "In univariate analyses, tumor length (P = 0.030), vessel invasion (P = 0.010), perineural invasion (P = 0.034), TNM stage (P < 0.001), NLR (P < 0.001), CRP (P < 0.001), Alb(P = 0.001), GPS (P < 0.001), CRP/Alb (P < 0.001) and NLR/Alb (P < 0.001) were also significant predictors of CSS." (PMID 29262582, 2017). "As CRP is a rather unspecific marker and does not reflect the types of immune cells present in ascites and tumors we performed in-depth analyses of the immunological and metabolic milieu in blood, ascites, and tumor tissue of these patients." (PMID 27665539, 2016). "However, according to our knowledge, our present study is the first to assess the serum concentrations of chemokine CXCL12 in relation to its specific receptor CXCR4 and classical tumor markers for EC (CEA and SCC-Ag) as well as marker of inflammatory states—C-reactive protein (CRP)." (PMID 27041792, 2016). "The identification of CRP and LBP in this study and IL-6 previously as indicators of response to radiotherapy suggests that inflammation could be an important factor in radiotherapy response either through tumour response or radiotherapy toxicity." (PMID 26425690, 2015). "Moreover, we have previously demonstrated that the non-normalization of postoperative CRP, pre-CRP elevation, microvascular invasion, and histological tumor necrosis were independent predictors for recurrence in N0M0 clear cell RCC." (PMID 25435945, 2015). "In univariate analysis, histological grade, T stage, modified N stage, PLR, NLR, LMR, GPS, mGPS and CRP/Alb were found to be significant prognostic factors, while age, sex, body mass index (BMI), tumor location, tumor length and examined lymph nodes showed no statistical differences." (PMID 26689680, 2015). "Glycosylation of CRP may differ in the carbohydrate and amino-acid sequences depending on the inducing pathological condition including infectious, non-infectious, and neoplastic diseases." (PMID 26380255, 2015). "In conclusion, we show that systemic inflammation, assessed by pre-operative CRP level at the time of diagnosis, may influence overall and disease-free survival in untreated node-negative patients, independent of tumor size, tumor grade, and molecular subtype." (PMID 25340395, 2014). "Moreover, pre-operative CRP levels did not correlate with age at diagnosis, tumor size, histological tumor grade, ER, PR status or HER2 status, proliferation index (Ki67), molecular subtypes, Ki-67, necrosis or inflammatory infiltrate." (PMID 25340395, 2014). "Whether STAT3-mediated upregulation of STAT1 and CRP actually supports or suppresses tumor growth is not clear to this point despite both STAT1 and CRP potentially having both pro- and anti-tumor activity." (PMID 24743777, 2014). "We analyzed the relationship between the expression of IL-8 in tumor cells, i.e., IL-8(T) and the patients’ peripheral blood data and found that there was a significant correction between IL-8(T) and the circulating C-reactive protein (CRP) level (P = 0.001) (Data not shown)." (PMID 25461761, 2014). "The mean CRP value was higher in patients with clinically suspicious and tumor-positive nodes than in those whose inguinal lymph nodes were clinically suspicious but eventually tumor negative (24.7 vs. 6.4 mg/l)." (PMID 24148787, 2013).
tumor (continued). "The combined value of SCC-Ag and CRP was significantly correlated with the combined value of SUVtumor-max and SUVnodal-max (P = 0.019), which indicates that the preoperative levels of SCC-Ag and CRP together represent a valuable marker for the evaluation of tumor aggressiveness in PLC." (PMID 23383155, 2013). "In contrast, a tumor stage ≥pT2 and a CRP value >15 mg/l failed to reach statistical significance." (PMID 23642165, 2013). "The gender, age, PS, CRP, tumor location, presence or absence of perinephric fat invasion/lymph node metastases/distant metastases, nuclear grade, and pathological tumor subtype were not significantly different among the levels of tumor thrombus." (PMID 24083566, 2013). "When baseline levels of CRP and NLR were analyzed for tumor response, there were more non-responders in the group with serum CRP > 6.3 mg/L and NLR > 2.3, whereas there were more good responders in the group with both baseline serum CRP ≤ 6.3 mg/L and NLR ≤ 2.3 (p < 0.001)." (PMID 23409924, 2013). "In all patients, regardless of tumor stage, there was an increase in the concentration of CRP." (PMID 23554823, 2013). "In addition to bivariate associations shown in the correlation analyses above, we found multivariate predictor sets for FACT-F (CRP and antidepressant intake; explained variance 26.3%; p = 0.001) and MAC-Fatalism (sex, age, tumor stage; explained variance 28.9%; p<0.001)." (PMID 22615854, 2012). "Furthermore, other recent studies indicated that CRP, next to prostate specific antigen (PSA), could serve as an additional independent prognostic marker for tumor-specific survival in metastatic castration-resistant prostate cancer." (PMID 22958305, 2012). "CRP is a nonspecific but sensitive marker of systemic inflammatory response, and might be expressed in selected tumor cells." (PMID 22103888, 2011). "Elevated CRP level may simply reflect a nonspecific inflammatory response to tumour necrosis or local tissue damage." (PMID 17211465, 2007). "However, in the present study, when the analysis was confined to those patients with stage I disease, neither C-reactive protein, interleukin-6 or interleukin-10 appeared to normalise on resection of the primary tumour." (PMID 17003778, 2006). "The presence of an elevated C-reactive protein concentration may simply reflect a nonspecific inflammatory response secondary to tumour necrosis or local tissue damage." (PMID 16721360, 2006). "In all patients, tumour grade was directly associated with Ki-67 labelling index (P<0.001), COX-2 expression (P<0.001), CD4+ (P<0.01) and CD8+ (P<0.001) T-lymphocytes, but not with C-reactive protein (P=0.152)." (PMID 17024120, 2006). "However, neither of these tumour-based factors was independently significant when a marker of the systemic inflammatory response (C-reactive protein) was included in the survival analysis." (PMID 17024120, 2006). "Moreover, radiomics features derived directly from tumor lesions may capture tumor heterogeneity more specifically and directly than indirect clinical parameters such as PD-L1 expression, BTS, and CRP, potentially accounting for their superior predictive efficacy." (PMID 41487592, 2025). "However, these indices often focus on a narrower subset of parameters—such as serum albumin and total lymphocyte count (PNI) or C-reactive protein and hypoalbuminaemia (mGPS)—and may not fully capture the complexities of the tumour–immune interplay." (PMID 40091005, 2025). "However, the inherent lack of specificity of CRP limits its utility as a standalone tumor marker, necessitating combinatorial approaches that integrate tumor-specific antigens (e.g., carcinoembryonic antigen, CEA) or advanced imaging techniques to enhance screening precision." (PMID 40563367, 2025). "Furthermore, DiR-labeled CRP-MC was used to determine whether modulating the tumor microenvironment with CRE-NP (α-M) could enhance the delivery and distribution of CRPPR-modified micelles in the tumor region." (PMID 36869341, 2023).